CDNF (cerebral dopamine neurotrophic factor)
Diseases named in the same sentence as CDNF in open-access papers (continued):
Sharing a sentence is not in itself a finding about the gene and the disease.
myocardial ischemia (1 paper, 2022). A disorder of cardiac function caused by insufficient blood flow to the muscle tissue of the heart. "In ER stress-related disease models in vivo, expression of endogenous CDNF was reported to increase after cerebral or myocardial ischemia." (PMID 34907395, 2022). "Protective effects of exogenous CDNF against myocardial ischemia/reperfusion injury was dependent on the presence of the C-terminal lysine-threonine-glutamic acid-leucine (KTEL) sequence and PI3K-Akt signaling pathway." (PMID 34907395, 2022).
osteosarcoma (1 paper, 2022). A usually aggressive malignant bone-forming mesenchymal neoplasm, predominantly affecting adolescents and young adults. "For example, an ER stress-induced increase in CDNF expression was detected in cardiomyocytes, but not in an osteosarcoma-derived cell line." (PMID 36012764, 2022).
neurodegenerative disease (11 papers, 2017 to 2025). A disorder of the central nervous system characterized by gradual and progressive loss of neural tissue and neurologic function. "Cerebral dopamine neurotrophic factor (CDNF) was shown to possess immune-modulatory properties that benefit neurodegenerative diseases." (PMID 35740467, 2022). "Deficiency of neurotrophic factors, such as cerebral dopamine neurotrophic factor (CDNF), neurturin and glial cell line-derived neurotrophic factor (GDNF) has also been related to neurodegenerative diseases." (PMID 35425456, 2022). "Neuroprotective effects of CDNF have been described in other models of neurodegenerative diseases, including PD37." (PMID 33154393, 2020). "Therefore, additional studies are required to further investigate physiological effect of selected miRNAs and contribution of MANF/CDNF in this effect in degenerative diseases." (PMID 34575854, 2021). "Both MANF and CDNF are protective and restorative in rodent models of neurodegenerative diseases." (PMID 31781038, 2019). "Since oxidative ER stress is an important pathway to cell death in neurodegenerative diseases, CDNF may limit disease progression." (PMID 28303260, 2017). "In addition, CDNF supplementation could enhance Arg1 expression in 6-OHDA-siumulated BV2 cell lines, suggesting that CDNF can boost microglial polarization toward anti-inflammatory phenotype serving as a reparative role in neurodegenerative diseases." (PMID 35740467, 2022). "Mesencephalic astrocyte-derived neurotrophic factor (MANF) and cerebral dopamine neurotrophic factor (CDNF) form a family of atypical growth factors discovered for their neuroprotective properties in the central nervous system (CNS) in animal models of neurodegenerative diseases." (PMID 31781038, 2019). "Cerebral dopamine neurotrophic factor (CDNF) and mesencephalic astrocyte-derived neurotrophic factor (MANF) display cytoprotective effects in animal models of neurodegenerative diseases." (PMID 35129674, 2022). "Since submaximal doses of two proteins, CDNF and GDNF, lead to full effect, less NTF is needed, less side effects will likely occur and possible drug therapy for degenerative diseases will be cheaper." (PMID 28303260, 2017). "Thus, one could consider how to increase endogenous levels of CDNF and MANF in humans to promote healthy aging and possibly prevent or delay the development of neurodegenerative diseases." (PMID 37555005, 2023). "Nevertheless, our findings suggest that CDNF is a modulator of 5-HT turnover, learning, and emotion-related behavior, and this property may be beneficial for the treatment of nonmotor symptoms in neurodegenerative diseases." (PMID 39408672, 2024).
neurological diseases (6 papers, 2019 to 2025). "However, the relationship between CDNF expression in platelets and the underlying pathophysiology of nervous system disorders remains unclear and requires further investigation." (PMID 39256999, 2024). "By targeting key pathways involved in ER stress regulation and neuronal survival, CDNF offers significant potential for treating neurological disorders where other neurotrophins fall short." (PMID 40827505, 2025). "The neurotrophic role of mesencephalic astrocyte derived neurotrophic factor (MANF) and cerebral dopamine neurotrophic factor (CDNF) has been demonstrated in several models of neurological diseases and crosstalk with BDNF and GDNF." (PMID 36338029, 2022). "The effect of CDNF on neurological diseases, especially PD, has been widely studied." (PMID 39019902, 2024). "Thus, CDNF-specific nano-thin layers of MIP were electrogenerated on sensing elements of surface acoustic wave (SAW) transducers and adopted for ultra-sensitive detection of CDNF protein for early diagnosis of neurological disorders and monitoring of neuroprotective therapies." (PMID 38391990, 2024). "CDNF and MANF have been shown to have therapeutic effects in various neurological disease models via administration of recombinant proteins or via the gene therapy approach." (PMID 31044581, 2019).
brain diseases (2 papers, 2020 to 2023). "For example, the cerebral dopamine neurotrophic factor possesses immune-modulatory properties that benefit brain diseases." (PMID 37187752, 2023). "It remains to be studied whether CDNF may increase either neurogenesis or the differentiation of neuroblasts in HD, as well as in other types of brain disorders." (PMID 33154393, 2020).
CDNF also shares sentences with these, for which no sentence is quoted: amyloid (1 paper); autism (1); autoimmune disease (1); brain infarct (1); brain injuries (1); cerebral infarction (1); multiple sclerosis (1); peripheral neuropathies (1); pneumonia (1); progressive neurodegenerative disorder (1); rheumatoid arthritis (1); systemic lupus erythematosus (1).